IL33 (interleukin 33)
Diseases named in the same sentence as IL33 in open-access papers (continued):
Sharing a sentence is not in itself a finding about the gene and the disease.
eosinophilia (continued). "In preliminary experiments we have observed that repetitive intratracheal administration of human IL-33 in mice induces lung eosinophilia, which can be prevented by treatment of mice with human IL-33trap." (PMID 32754154, 2020). "IL-33 was shown to both enhance airway eosinophilia and inflammation through ILC2 stimulation but also to lead to increased Treg number though MC and IL-228." (PMID 32286393, 2020). "Collectively, these data indicate that IL-33-responsive bone marrow ILC2s contribute to allergen-induced bone marrow and airway eosinophilia." (PMID 32582171, 2020). "Our data suggest that ILC2s are the predominant IL-33-responsive cell type active at the onset of allergen-induced eosinophilia, as indicated by the correlation between ST2 expression on ILC2s and the induction of eosinophil progenitors." (PMID 32466530, 2020). "We conclude that IL-33 plays important roles for the initiation of bone marrow eosinophilia where IL-33-responsive bone marrow ILC2s contribute to allergen-induced IL-5-dependent eosinophilic inflammation." (PMID 32582171, 2020). "A striking result in our study was that Rag2−/−Il2rg−/− mice displayed a reduced number of bone marrow eosinophils at baseline and were unable to develop bone marrow eosinophilia in response to IL-33 challenge." (PMID 32582171, 2020). "Short term exposure to intranasal IL-33 induces ILC2 dependent eosinophilia and lung inflammation characteristic of allergic asthma in absence of T cells." (PMID 31620118, 2019). "Similar to Il33−/− mice, Il25−/− mice and Crlf2−/− mice showed attenuated airway eosinophilia after FAP inhalation, suggesting that IL-25 and TSLP, in addition to IL-33, are involved in FAP-induced airway eosinophilia." (PMID 30575775, 2018). "The asthmatic airway epithelium also produced specific cytokines favoring Th2 and/or Th17 cell differentiation, such as IL-33-promoting IL-5 production and eosinophilia." (PMID 30380761, 2018). "Il33−/− mice showed attenuation of induction of OVA-induced airway eosinophilia in the presence of chitin, indicating that IL-33 is crucial in the setting." (PMID 30082755, 2018). "The airway epithelium can also produce specific cytokines favoring Th2 and/or Th17 cell differentiation, such as IL-33 promoting IL-5 production and eosinophilia." (PMID 30380761, 2018). "For example, early work concluded that IL-33-induced eosinophilia was dependent on IL-5, but this conclusion was based largely on a neutralizing antibody approach and limited markers for defining eosinophils." (PMID 28512632, 2017). "In contrast, while IL-33 increased lung eosinophils in Rag1–/– mice, animals treated with IL-33 and IL-2c had a significant reduction in lung eosinophilia." (PMID 29196657, 2017). "In mouse studies addressing this question, IL-33 from macrophages, DCs, and monocytes are sufficient to support the development of Th2 responses and eosinophilia." (PMID 28512632, 2017). "Further research is certainly required to determine how eosinophil progenitors contribute to tissue eosinophilia in disease and if IL-33 serves to initiate their responses." (PMID 28512632, 2017). "Although a role for IL-33 in the induction of IL-5 and eosinophilia was first proposed at that time, these effects were attributed to the production of IL-5 by Th2 cells." (PMID 28751971, 2017). "Airway eosinophilia and Th2 cell recruitment, which was reduced in Ccsp-creTgfb1−/− mice, was elevated to comparable levels as control IL-33-treated mice." (PMID 26588780, 2015). "It attenuated OVA-induced lung tissue eosinophilia and airway mucus production, mRNA expression of E-selectin, IL-17, IL-33 and Muc5ac in lung tissues, and airway hyperresponsiveness to methacholine." (PMID 21695271, 2011). "Schmitz and co-workers demonstrated that injection of IL-33 into mice induces a profound eosinophilia, and has potent effects on this cell type, including induction of superoxide anion and IL-8 production, degranulation and cell survival." (PMID 21871091, 2011).
eosinophilia (continued). "In animals, IL-33 treatment induces the expression of IL-4, IL-5 and IL-13 in the lung and intraperitoneal injection of IL-33 induces spleen eosinophilia." (PMID 18315837, 2008). "Recent work in neutralising Hps immunomodulatory secretions suggests that IL‐33 is capable of promoting expulsion, although whether through ILC2s, T cells, or indeed macrophages or eosinophilia remains unclear at this time." (PMID 40944312, 2025). "In one of our previous studies, we showed that IL-33 may promote airway eosinophilia in COPD patients through stimulation of in situ differentiation of hematopoietic precursor cells into eosinophils." (PMID 39452061, 2024). "Indeed, mice injected with IL-33 exhibit significant pathological changes in mucosal tissues, including eosinophilia in the lung, esophagus, and intestine, as well as elevated serum levels of IgA and IgE." (PMID 38337546, 2024). "Likewise, shellfish-derived chitin administered once, twice, or three times can drive IL-33-dependent eosinophilia." (PMID 38915287, 2024). "Immune factors leading to eosinophilia, including the constitutive production of IL-25/IL-33/TSLP by epigenetically modified airway epithelial cells may be less influenced by ETI and may remain constant." (PMID 37525180, 2023). "However, mast cells alleviate the inflammatory effect in some cases; it has been reported that IL-33-stimulated IL-2 production by mast cells promotes an increase in the number of Tregs in eosinophilia induced by papain or IL-33." (PMID 38082335, 2023). "Rag2−/−Il2rg−/− mice, which lack B, T, and NK cells, reconstituted with WT ILC2s and intranasally challenged with IL-33 and GTS-21 and exhibited reduced airway hyperreactivity (AHR) and eosinophilia compared to the mice reconstituted with α7nAChR-deficient ILC2s." (PMID 36704754, 2022). "Thus, RBM3 directly suppresses lung ILC activation by IL-33 in vitro and in vivo, and this leads to significant differences in eosinophilia and neutrophilia in vivo." (PMID 35908044, 2022). "Taken together, reduced expression of CCR3 on eosinophils and CCL24/eotaxin-2 in the airways could potentially explain the decrease in airway eosinophilia observed in mice given rapamycin in addition to IL-33." (PMID 35720347, 2022). "Whether IL-25 and IL-33-mediated eosinophilia occurs in other subtypes of CRC inhibiting tumorigenesis remains to be established, however unlike CAC, most studies are concordant with IL-25 and IL-33 promoting tumorigenesis in APC-mutation-mediated CRC." (PMID 36263033, 2022). "The results demonstrate that, at the systemic level, the IL-33/ST2 pathway is important for the establishment of eosinophilia and for the increase of monocytes in T. canis infection, in addition to contributing to the production of IgG1, IgG2a and IgG2b antibodies." (PMID 34324507, 2021). "Given that IL-33 induces type-2 cytokines from ILC2, the attenuated eosinophilia in ob/ob mice may have been associated with a decrease in IL-5, IL-13, and eotaxin." (PMID 34074279, 2021). "The first report, which designated IL-33 as a member of the IL-1 superfamily, described that injection of IL-33 (0.4 or 4 μg daily) in mice for a short time (up to 7 days) induces splenomegaly, eosinophilia and serum IgE as well as pathological changes in the lung and the digestive tract." (PMID 34948083, 2021). "Collectively, our results demonstrate that the Th2 immune response triggered by IL-33/ST2 pathway mediates susceptibility to T. canis, related to parasitic burden, eosinophilia and granuloma formation in which consequently contributes to tissue inflammation and injury." (PMID 34324507, 2021). "ILC2s are critical for the development of eosinophilic hepatitis and induction of fibrosis-related gene expression in the IL-33 treated mice as the ILC2-deficient CD127 cKO mice showed much reduced or no sign of eosinophilia and fibrosis." (PMID 34305911, 2021).
eosinophilia (continued). "We hypothesized that IL-33 was critical for the increased mucus, eosinophilia, and TH2 cytokine production during RSV infection in OVA-allergen challenged mice." (PMID 34266437, 2021). "IL-33 can induce eosinophilopoiesis and enhance EoP migration, suggesting that the blockade of the IL-33/ST2 axis may result in impaired airway eosinophilia." (PMID 33669458, 2021). "The presence of the IL-33/ST2 pathway increases eosinophilia and eosinophilic activity in tissues, increases the hepatic and cerebral parasitic burden and contributes to the formation of hepatic and pulmonary granuloma, which does not control larval migration nor causes tissue damage." (PMID 34324507, 2021). "Our results suggested that the IL-33/ST2 pathway in T. canis infection is important for the establishment of eosinophilia and its presence is related to hepatic and cerebral parasitic tropism, with increased liver and lung tissue inflammation, with loss of function." (PMID 34324507, 2021). "However, the contribution of IL-33-responsive ILC2s in allergen-induced bone marrow eosinophilia remains to be determined." (PMID 32582171, 2020). "The authors reported that IL-33 deficiency increased S. venezuelensis faecal egg release at day 8 p.i. and simultaneously abrogated lung ILC2 expansion, IL-5 production and lung eosinophilia, while i.n. application of recombinant IL-33 rescued these features in IL-33-/- mice." (PMID 33351862, 2020). "Furthermore, our data suggest a critical role for IL-33-responsive ILC2s at the onset of allergen-induced bone marrow eosinophilia." (PMID 32466530, 2020). "Indeed, a positive relationship between IL-33 and eosinophilia has been demonstrated in several studies, including reports of lower baseline levels of eosinophils in peripheral blood in knock out mice that lack IL-33 or the IL-33 receptor (ST2)." (PMID 32582171, 2020). "IL-33 drives substantial eosinophilia in vivo, although it is unclear whether this effect occurs via a direct or indirect mechanism." (PMID 31717819, 2019). "Given the IL-33-mediated switch toward the gut eosinophilia, we questioned whether IL-33 treatment also altered the cytokine milieu during CDI." (PMID 31221971, 2019). "Bone marrow ILC2s has been shown to be a local source of IL-5 in IL-33-driven eosinophilia." (PMID 30886621, 2019). "Furthermore, serum and sputum IL-33 levels were higher in COPD subjects with sputum eosinophilia than in those with a sputum eosinophil count ≤3% (p < 0.001 for both)." (PMID 29859068, 2018). "In addition, serum IL-33 levels were found to be significantly higher in the subgroup of COPD patients with sputum eosinophilia (43.98±4.76 pg/ml) compared to those with a sputum eosinophil level ≤3% (29.15±2.01 pg/ml; p < 0.001)." (PMID 29859068, 2018). "In addition, IL-33 stimulates type 2 innate lymphoid cells to produce IL-5 and -13 resulting in eosinophilia and goblet cell hyperplasia, respectively." (PMID 30176857, 2018). "Likewise, we found that epithelial cell-derived IL-33 was important for development of FAP-induced airway eosinophilia." (PMID 30575775, 2018). "In conclusion, our results suggest that increased IL-33 is associated with airway eosinophilia in non-atopic COPD." (PMID 29859068, 2018). "IL-33 initiates allergic inflammation by activating innate lymphoid cells type 2 (ILC2s) to produce large amounts of Th2 cytokines IL-5 and IL-13 responsible for eosinophilia and IgE-class switching, respectively." (PMID 29416104, 2018). "Administration of IL-33 is sufficient to drive in vivo eosinophilia in various tissues." (PMID 28512632, 2017). "In the present study, we clearly demonstrated that airway eosinophilia was significantly reduced in EC sensitized IL-25-/- mice and EC sensitized IL-33-/- mice compared with EC sensitized WT mice, indicating that both IL-25 and IL-33 are crucial for development of airway inflammation in the setting." (PMID 26230091, 2015).
eosinophilia (continued). "The eosinophilia was dependent on serine protease activity of Alternaria and contingent on IL-33." (PMID 24636086, 2014). "However, in a model of autoimmune heart disease treatment with IL-33 induced eosinophilic pericarditis and cardiac dilation, whereas sST2 prevents eosinophilia and improves systolic function." (PMID 24751794, 2014). "Moreover, exogenous administration of recombinant IL-33 in mice led to Th2-mediated immune responses, inducing eosinophilia, splenomegaly, goblet cell hyperplasia and mucus production at mucosal surfaces, and increased serum levels of IL-5 and IgE." (PMID 23062310, 2012). "Furthermore, intranasal IL-33 also promotes airways hyper-responsiveness, goblet cell hyperplasia, eosinophilia, polarization of macrophages towards an M2 phenotype, and accumulation of lung IL-4, IL-5 and IL-13." (PMID 21871091, 2011). "Similarly, exogenous IL-33 application provides a mechanistic rationale for EoE development in mice, promoting transmural eosinophilia, mucosal hyperproliferation, upregulation of eosinophilic genes and chemokines, and the inhibition of the regulatory T cell with loss of antigenic tolerance." (PMID 37048784, 2023). "Therefore, we examined whether TSLP, IL-25 and/or IL-33 contribute to induction of eosinophilia in the BAL fluid of mice after inhalation of large-size chitin (70–100 μm)." (PMID 33723298, 2021). "This implicates IL-33 in the regulation of allergen-induced bone marrow eosinophilia and opens the possibility that IL-33 activates eosinophils and other immune cells in the bone marrow that express ST2, which may contribute to eosinophilic airway inflammation." (PMID 32466530, 2020). "In addition, when eosinophilia subsides, the endometrium reacts with fibrosis establishment, which could be stimulated by the pro-fibrotic cytokine IL33, whose release might then be ascribed to fibroblasts." (PMID 33134338, 2020). "Thus, we examined the contribution of IL-33-induced eosinophilia to worm expulsion." (PMID 24678315, 2014). "They all bind IL-33; HpARI1 and HpARI2 suppress ILC2 responses and eosinophilia while HpARI3 enhances ILC2 activity and eosinophilia following exposure to Alternaria allergen." (PMID 40565065, 2025). "Targeting upstream alarmins—through agents such as itepekimab (anti-IL-33) and anti-TSLP antibodies—shows promise in mitigating tissue eosinophilia and broad inflammatory cascades before they fully develop." (PMID 40732309, 2025). "This was in contrast to mice exposed to IL-33 alone or in combination with HDM + OVA, which displayed a significant eosinophilia that likely also involves local ILC2 activation." (PMID 37612281, 2023). "Inflammation with eosinophilia is regulated by the chemokines CCL11 and the cytokines IL-13, IL-5, and IL-33." (PMID 36970065, 2023). "Some studies have already shown that IL-33 plays an important role in the pulmonary Th2 profile, activating type 2 innate lymphoid cells (ILC2) and increasing eosinophilia." (PMID 36145419, 2022). "RSV driven IL–33–activated ILC2 is crucial for the development of airway inflammation, including eosinophilia and airway hyperreactive response, through ILC2–specific IL–13 production." (PMID 35603159, 2022). "IL1RL1, a membrane receptor whose expression is continuously upregulated during the progression of T2D, can bind to IL-33 to activate the TH2 inflammatory response and eosinophilia." (PMID 36248223, 2022). "The aim of this study was to determine the role of the mTORC1 signaling pathway in IL-33-induced bone marrow ILC2 responses and its impact on IL-33-induced eosinophilia." (PMID 35720347, 2022). "B6 mice only showed a significant upregulation in AHR, eosinophilia, ILC2s, and type 2 cytokine production in the lung and BAL fluid when intranasally challenged with NMU and IL-33 or IL-25 together than when alone." (PMID 36704754, 2022).
eosinophilia (continued). "To determine the role of rapamycin in eosinophilia, we administered rapamycin to C57BL/6 male mice before inducing eosinophilic inflammation by IL-33." (PMID 35720347, 2022). "Both papain and IL-33 have been shown to induce ILC2-dependent IL-5 and IL-13 production and airway eosinophilia." (PMID 34194431, 2021). "IL1RL1 is the receptor for interleukin‐33 (IL‐33) which acts as a selective chemoattractant of Th2 cells, and elicits IL5‐dependent eosinophilia." (PMID 33295083, 2021). "Like ILC2del mice, IL4Rα–/– x IL5Tg and STAT6-–/– x IL5Tg mice were protected from pulmonary hemorrhage after IL-33 administration and had dramatically reduced BAL eosinophilia compared with controls." (PMID 33974563, 2021). "ILC2del x IL5Tg mice were protected from pulmonary hemorrhage after IL-33 and had dramatically blunted BAL eosinophilia despite insignificant changes in peripheral eosinophilia." (PMID 33974563, 2021). "Anti-HMGB1 and anti-IL-33 treatment of IRF7-/- mice decreased ILC2 numbers in the lung, type-2 cytokine responses in BALF, and airway eosinophilia." (PMID 32658914, 2020). "Already evidence is suggesting that certain helminth extracellular vesicles are capable of modulating the IL-33/ST2 signaling pathway, which has the capability of suppressing ILC2 accumulation and eosinophilia resulting in an abrogated allergic response." (PMID 32363166, 2020). "Although IL-33 treatment significantly induced eosinophilia in the BAL of WT and PD-1 KO mice, the number of eosinophils was significantly higher in IL-33-treated PD-1 KO mice compared to WT mice." (PMID 32778730, 2020). "Both induce a significant increase in lung/airway IL-33, IL-33 dependent ILC2 activation, type-2 cytokine release and eosinophilia." (PMID 31024526, 2019). "Accordingly, there was increased expression of Muc5ac, pro-Th2 and Th17 cytokine (e.g., Il13, Il33 and Il17a), increased BALF eosinophilia, as well as increased genes involved in epithelial repair responses in the lungs (e.g. Egfr and Tff2)." (PMID 31089182, 2019). "Intranasal administration of IL-33 induced rapid and robust type 2 responses characterized by ILC2 accumulation, type 2 cytokine secretion, eosinophilia and goblet cell metaplasia." (PMID 29593738, 2018). "They identified that IL-33 with IL-5, produced by ILC2, mediates the effect by induction of eosinophilia." (PMID 29163523, 2017). "But the fact that the frequency of ILC210 strongly correlated with the extent of ILC activation and eosinophilia, suggests that ILC210 production is a byproduct of highly inflammatory conditions, as would be mimicked by direct injection of IL-33." (PMID 29196657, 2017). "Both types of mice after infection almost equally increased the number of IL-33-expressing ATII cells and developed lung eosinophilia, indicating that acquired immune cells are dispensable for IL-33-induced eosinophil accumulation in the lungs." (PMID 24678315, 2014). "Overall eosinophilia during ICI therapy may predict subsequent irAEs, and tumor–eosinophil cross-talk (enhanced by IL-5/IL-33) is increasingly recognized as integral to both therapeutic responses and collateral immune adverse events." (PMID 40723182, 2025). "In contrast to mice treated with the control IgG antibody to SLPI KO mice, SLPI KO mice treated with anti-IL-33 neutralizing antibody showed reduced airway inflammation and fewer numbers of BAL total cells, ratio of eosinophilia, and Th2 cytokines (e.g., IL-5 and IL-13) in BAL fluid." (PMID 40546642, 2025). "Although lung eosinophilia was established in the absence of IL-33, BAL eosinophil numbers were reduced in HDM-sensitized IL-33KO mice compared to IL-33WT animals." (PMID 37612281, 2023). "Interestingly, Rag2−/− mice challenged with IL-33 and CGRP had reduced immune-cell infiltrates, eosinophilia, goblet cell hyperplasia, and type 2 cytokine levels in the lung tissue and BAL fluid compared to the IL-33 treated control." (PMID 36704754, 2022).